EGF (epidermal growth factor)
Diseases named in the same sentence as EGF in open-access papers (continued):
Sharing a sentence is not in itself a finding about the gene and the disease.
colorectal cancer (continued). "Our own work recently reinforced these studies, describing that gastric and colorectal cancer cell motility, proteolysis and invasion are stimulated by macrophages and that epidermal growth factor (EGF) is a key molecule in this crosstalk." (PMID 26043921, 2015). "The discovery that the epidermal growth factor (EGF) pathway in colorectal cancer was sensitive to inhibition by anti‐EGF receptor (EGFR) monoclonal antibodies (mAbs) led to the rapid development of panitumumab and cetuximab." (PMID 25627134, 2015). "For example, in colorectal cancer cells, epidermal growth factor (EGF) increased expression of cyclooxygenase-2 via STIM1 and Orai1." (PMID 24586666, 2014). "Claudin-2 overexpression has been shown to relate to epithelial weakening in lung and colorectal cancer cells, and these events are regulated by EGF-mediated signaling pathways." (PMID 24069372, 2013). "In conclusion, our results show a novel role for claudin-3 overexpression in promoting the malignant potential of colorectal cancer cells, which is potentially regulated by the EGF-activated ERK1/2 and PI3K-Akt pathways." (PMID 24069372, 2013). "The EGF pathway is considered to be the most prominent signaling pathway in colorectal cancer, as it regulates the differentiation, survival, proliferation and migration of cancer cells." (PMID 23420529, 2013). "Together, these data show that EGF enhances events related to the malignant potential of undifferentiated colorectal cancer cells." (PMID 24069372, 2013). "We have previously reported that the blockade of EGF stimulation significantly suppressed colorectal cancer cell growth, suggesting that the EGFR pathway plays an important role in proliferation of these cells." (PMID 22788833, 2012). "In this study,human colorectal cancer cells treated with HDACi exhibited reduced EGFRexpression, thereby disturbed EGF-induced ERK and Akt phosphorylation." (PMID 21464950, 2011). "Moreover, EGF increases lipid droplet density in colorectal cancer cells through PI3K/mTOR signalling." (PMID 39433211, 2025). "EGF treatment promotes the Na+-dependent uptake of glutamine in colorectal cancer cells." (PMID 39433211, 2025). "FUT2 was significantly suppressed during the EGF- or bFGF-triggered EMT of colorectal cancer cells." (PMID 36973740, 2023). "Since LiCl inhibited the tumorigenic effects of EGF, this cation might have tumor suppressor activity in colorectal cancer." (PMID 36836894, 2023). "EGF-targeted λ phage inhibit the growth of HT-29 colorectal cancer spheroids." (PMID 36591314, 2022). "N8-acetylspermidine and propionic acid increased EGF signaling genes expression, suggesting that they might directly promote cell proliferation of colorectal cancer cells." (PMID 33430687, 2021). "Our data suggest that CAF composition is important for cetuximab response, specifically highlighting EGF secretion by cetuximab treated CAFs as a previously unknown mechanism of resistance to anti-EGFR treatment in colorectal cancer." (PMID 32481658, 2020). "The aim of this study was to investigate the effector mechanisms of FAK in the process of EGF-induced EMT in colorectal cancer cells and to determine whether miR-217 is involved in this process." (PMID 32148496, 2020). "It has not yet been determined whether FAK is involved in the regulation of EMT in colorectal cancer cells through the EGF/EGFR signaling pathway." (PMID 32148496, 2020). "Furthermore, cells were also transfected with FAK siRNA and examined the migration and invasion abilities of EGF-induced colorectal cancer cells." (PMID 32148496, 2020). "The specific mechanism of this process involves the binding of EGF to EGFR, causing FAK phosphorylation, upregulation of miR-217 expression, and downregulation of E-cadherin; this induces EMT and enhances the migrating ability of colorectal cancer cells." (PMID 32148496, 2020).
colorectal cancer (continued). "Epidermal Growth factor (EGF) could induce colorectal cancer (CRC) cell to develop epithelial mesenchymal-transition and enhance their ability to invade and migrate." (PMID 31053624, 2019). "In addition to these assays, the specific phosphorylation of tyrosine 1068 (pY1068) of the epidermal growth factor receptor (EGFR) was quantified upon stimulation with EGF in HCT116 colorectal carcinoma cells." (PMID 29599435, 2018). "Additionally in this model, epidermal growth factor (EGF), whose signaling plays a critical role in colorectal cancer tumorigenesis, can stimulate p130Cas Y128 phosphorylation." (PMID 27240404, 2016). "ERK2 and TOPK phosphorylate each other upon exposure to EGF in colorectal cancer." (PMID 26745678, 2016). "Since anti-EGFR targeted therapies such as cetuximab and panitunumab improve tumor response when used in combination with irinotecan in colorectal cancer, it will be interesting to determine the effect of the EGF pathway and of these antibodies on PLCs emergence." (PMID 25565667, 2015). "To verify the hypothesis that ARNO is related to colorectal cancer by activating EGF and IGF, we performed immunohistochemistry of resected human colorectal adenocarcinomas stained by ARNO, pEGFR, and pIGF-IR." (PMID 24618737, 2014). "In conclusion, cytohesins play an essential role in the activation of the EGF pathway and may be a potential target in colorectal cancer therapy." (PMID 23420529, 2013). "The aim of the present study was to investigate whether cytohesins contribute to the epidermal growth factor (EGF) pathway in colorectal cancer cells." (PMID 23420529, 2013). "A different receptor, the epidermal growth factor, was also targeted for colorectal cancer treatment using monoclonal antibodies, enabling the growth inhibition of cancer cells; the antibodies cetuximab and panitumumab were the first therapeutic agents used in clinical trials for colorectal cancer." (PMID 35163122, 2022). "Therefore, this study aims to investigate whether FAK is involved in the regulation of colorectal cancer cells through the promotion of EMT via the EGF/EGFR signaling pathway and the enhancement of migration ability." (PMID 32148496, 2020). "Furthermore, ongoing work is focusing on potential dual-targeting of receptor tyrosine kinases that may be activated in colorectal cancer cells in response to increased exogenous EGF." (PMID 32481658, 2020). "However, whether FAK participates in EMT in colorectal cancer cells through the EGF/EGFR signaling pathway remains unknown." (PMID 32148496, 2020). "Moreover, FAK was involved in the EGF-induced EMT of colorectal cancer cells." (PMID 32148496, 2020). "The strongest impairment of cellular viability in our analyses, however, was observed upon treatment with the Pan-ErbB inhibitor afatinib, suggesting that other members of the ErbB family may be involved in EGF-mediated oncogenic signaling in colorectal cancer cells." (PMID 31488078, 2019). "In colorectal cancer, a high CXCL1/5 expression is maintained via the CXCR/MMPI/epidermal growth factor (EGF) pathway." (PMID 40076892, 2025). "Colorectal cancer cells were cultured in DMEM/F12 medium containing 2% B27, 10 ng/mL bFGF, and 20 ng/mL EGF, and using a low-adsorption plate, differentiated cells were disrupted in the medium, and undifferentiated cells formed spheres." (PMID 36824410, 2023). "Epidermal Growth Factor (EGF) and EGFR levels are significantly higher in malignant zones of colorectal cancer specimens than in other nearby regions." (PMID 37296986, 2023). "Monoclonal antibodies and tyrosine kinase inhibitors constitute new, moderately successful therapeutic options for UICC stage IV colorectal cancer patients and target VEGF and EGF signaling." (PMID 36264073, 2022). "ORAI1 also regulates EGF-mediated and lipopolysaccharide-mediated PTGS2 gene expression in colorectal cancer cell lines and AGS gastric adenocarcinoma cells, respectively." (PMID 35682546, 2022).
colorectal cancer (continued). "Noteworthily, silencing of SPP1 in epidermal cells increased the chemoattractant effect of epidermal growth factor (EGF), and overexpression of microRNA miR-27a reduced SPP1 levels, leading to a promotion of colorectal cancer." (PMID 34357010, 2021). "EGF upregulated the expression of E-cadherin in colorectal cancer cells by activating FAK, and miR-217 was found to participate in EGF-induced EMT in colorectal cancer cells." (PMID 32148496, 2020). "This study demonstrated that EGF/EGFR can phosphorylate FAK and induce EMT in colorectal cancer cells." (PMID 32148496, 2020). "Numerous factors can induce EMT in tumor cells including EGF, which initiates EMT in colorectal cancer cells through the EGF/EGFR signaling pathway, thereby facilitating invasion and metastasis." (PMID 32148496, 2020). "Our findings indicate that EGF induces EMT in colorectal cancer cells by activating FAK, and miR-217 is involved in the EGF/FAK/E-cadherin signaling pathway." (PMID 32148496, 2020). "Epithelial-mesenchymal transition (EMT) plays an important role in the invasion and metastasis of colorectal cancer, which is mediated by FAK and EGF." (PMID 32148496, 2020). "This also led to a significant decrease in the number of migrating cells, indicating that FAK is involved in the process of EGF-induced EMT and is related to colorectal cancer invasion and metastasis." (PMID 32148496, 2020). "We observed the activation of FAK by EGF and upregulation of miR-217 expression in Caco-2 cancer cells, resulting in the downregulation of E-cadherin and induction of EMT in colorectal cancer cells." (PMID 32148496, 2020). "Correspondingly, the expression of the pro-survival form of Fas enhanced the EGF-induced phosphorylation of STAT3, which is important for the cancer-promoting activities, such as migration of colorectal cancer cells." (PMID 30127519, 2018). "With EGF treatment, TOPK and ERK2 can phosphorylate each other, and lead to a positive feedback loop between TOPK and ERK2 in colorectal cancer." (PMID 26745678, 2016). "EGF/EGFR axis triggered EMT in cholangiocarcinoma cells, and β-catenin targeted EMT to promote metastasis in colorectal cancer cells." (PMID 27050434, 2016). "Overexpression of NDRG4 in colorectal cancer cell can significantly suppress PI3K-AKT activity, even after EGF stimulation." (PMID 25749388, 2015). "This study found that ARNO (cytohesin-2), an activator of the EGF and IGF-I pathways, was more highly expressed in colorectal cancer tissue than in benign adjacent colorectal tissue." (PMID 24618737, 2014). "To select EGFR/IGF-sensitive cell lines, we performed MTT assay by culturing the colorectal cancer cell lines HT29, SW620, SW480, HCT116, and LOVO in 1% FBS with EGF or IGF." (PMID 24618737, 2014). "For instance, human epidermal growth factor (EGF) upregulates AQP3 expression, thereby enhancing colorectal cancer cell migration via the phosphoinositide 3-kinase (PI3K)/Akt signaling pathway, being also associated with metastasis in colorectal cancer patients." (PMID 39941100, 2025). "The mutated organoids were also provided with a culture environment containing inhibitors of Wnt, R-spondin, epidermal growth factor (EGF), and bone morphogenetic protein/transforming growth factor-β, which are essential for colorectal cancer (CRC) organoids of patient origin." (PMID 40129676, 2025). "In addition, ligands such as epidermal growth factor(EGF), transforming growth factor alpha(TGFα), and two‐regulator proteins have been found in the EV of breast and colorectal cancer cell lines." (PMID 39015555, 2024). "Intriguingly, unlike EGF and EREG, NRG1 failed to support the growth of pre-tumorigenic intestinal organoids lacking the tumor suppressor Apc, commonly mutated in human colorectal cancer (CRC)." (PMID 36912192, 2023).
colorectal cancer (continued). "Epidermal-growth-factor (EGF)-induced extracellular signal-regulated kinase 2 (ERK2) activation phosphorylates CSN6 at S148, leading to β-catenin stabilization through blocking β-TrCP and colorectal cancer development." (PMID 37686524, 2023). "For example, epidermal growth factor (EGF) increases the activation of STAT3 through its phosphorylation, thus inducing HIF-1α upregulation and promoting the proliferation and metastasis of colorectal cancer cells." (PMID 34365889, 2021). "Huang et al37 also showed that PEAK1 expression was high in colorectal cancer tissues and that PEAK1 silencing could inhibit proliferation, migration, and invasion of colorectal cancer cells and significantly attenuate EGF‐induced p‐ERK1/2 expression levels." (PMID 32167655, 2020). "Full-length N-term-out functional EGFR ligands Amphiregulin (AREG), heparin binding EGF (HB-EGF) and transforming growth factor alpha (TGF)-α were first identified in sEVs derived from a panel of breast and colorectal cancer cell lines using fluorescence-activated vesicle sorting (FAVS)." (PMID 33228060, 2020). "The specific mechanism is the binding of EGF to EGFR, which activates downstream signaling pathways, leading to the downregulation of E-cadherin and upregulation of vimentin, thereby inducing EMT in colorectal cancer cells." (PMID 32148496, 2020). "Likewise, in human SW480 cells of colorectal carcinoma, the sialylation of EGFR decreases EGF-mediated cell proliferation." (PMID 33238647, 2020). "Our finding that the survival signaling pathways of Fas could be promptly activated by EGF, the cognate ligand of the EGFR, signifies a close connection between the two pathways in colorectal cancer cells." (PMID 30127519, 2018). "Thus cytohesins or ARNO was strongly correlated with EGF and IGF pathway activation in colorectal cancer." (PMID 24618737, 2014). "Colorectal cancer (CRC) is characterised by hypoxia, which activates gene transcription through hypoxia-inducible factors (HIF), as well as by expression of epidermal growth factor (EGF) and EGF receptors, targeting of which has been demonstrated to provide therapeutic benefit in CRC." (PMID 24180698, 2013). "We analyzed the influence of 8 germinal polymorphisms of candidate genes potentially related to EGFR signalling (EGFR, EGF, CCND1) or antibody-directed cell cytotoxicity (FCGR2A and FCGR3A) on outcome of colorectal cancer (CRC) patients receiving cetuximab-based therapy." (PMID 22117530, 2011). "No cases of colorectal cancer have been reported after EGF therapy for IBD, probably because of the small number of patients included in trials." (PMID 19636186, 2009). "We have recently conducted a phase II study: Gefitinib (Iressa®) in combination with FOLFOX4 regimen in EGF-positive advanced colorectal cancer not pre-treated for advanced disease." (PMID 22275961, 2008). "In the late stages of colorectal cancer (CRC) tumors, TGF-β is highly expressed and acts as a tumor promoter, as the production of several growth factors such as Transforming Growth Factor-α (TGF-α), Fibroblast Growth Factor (FGF) and Epidermal Growth Factor (EGF) is increased." (PMID 38339232, 2024). "Certain indications suggest that EGFR and its ligands (epidermal growth factor (EGF), amphiregulin, HB-EGF, TGF-alpha) can be applied as serological biomarkers in relation to the prognosis and prediction of response to EGFR-targeted treatments in lung, ovarian, and colorectal cancer." (PMID 37626832, 2023). "Moreover, the results of this study showed that EGF induced FAK phosphorylation in Caco-2 cancer cells, and FAK inhibitors could inhibit EGF-induced FAK phosphorylation in colorectal cancer." (PMID 32148496, 2020). "Furthermore, EGFR inhibition by erlotinib, a small molecule inhibitor that binds to the intracellular tyrosine kinase domain, or treatment with oxaliplatin, a chemotherapy used to treat colorectal cancer, did not initiate increased secretion of EGF." (PMID 32481658, 2020).
colorectal cancer (continued). "This counterintuitive result was well exemplified by the cases of ZEB2 and RAS in the EMT regulatory network, IRS in the signaling network of EGF-EGFR and insulin-IR, MEK and GRB2 in the signaling network of T-LGL leukemia survival, p21 and PDK1 in F2013, and MEK in C2016 colorectal cancer networks." (PMID 31582789, 2019). "However, there have been no reports thus far on whether miR-217 is involved in EGF-induced EMT in colorectal cancer cells." (PMID 32148496, 2020). "Interestingly, we identified multiple colorectal cancer spheroid lines that depended on bFGF for their growth rather than on EGF, suggesting that FGFR inhibitors may suppress the growth of CRC-TICs, through blocking the Ras/Raf/ERK pathway." (PMID 29774115, 2018). "Our results provide some of the first evidence for PDGF cross-signaling through alternative receptors in colorectal cancer and support anti-PDGF therapy as a combination strategy alongside VEGF and EGF targeting even in tumors lacking PDGFR expression." (PMID 36264073, 2022). "EGF was previously shown to regulate the EMT markers E-cadherin and Vimentin in mesothelioma cells and colorectal cancer cells but failed to do so in A549 cells." (PMID 33777943, 2021). "EGF-liposome conjugates remarkably reduced the IC50 value of oxaliplatin in colorectal cancer cells which overexpressed ERFR, though not in the EGFR-negative colorectal cancer cells." (PMID 36983571, 2023). "Therefore, tactics targeting EGF/EGFR cascade system would have been an effective and timely approach for clinical prevention and therapeutic intervention for the transition from chronic non-resolving UC to pernicious colorectal carcinoma." (PMID 23825635, 2013).